PHF1 (PHD finger protein 1)
Description:
Polycomb group (PcG) that specifically binds histone H3 trimethylated at 'Lys-36' (H3K36me3) and recruits the PRC2 complex. Involved in DNA damage response and is recruited at double-strand breaks (DSBs). Acts by binding to H3K36me3, a mark for transcriptional activation, and recruiting the PRC2 complex: it is however unclear whether recruitment of the PRC2 complex to H3K36me3 leads to enhance or inhibit H3K27me3 methylation mediated by the PRC2 complex. According to some reports, PRC2 recruitment by PHF1 promotes H3K27me3 and subsequent gene silencing by inducing spreading of PRC2 and H3K27me3 into H3K36me3 loci. According to another report, PHF1 recruits the PRC2 complex at double-strand breaks (DSBs) and inhibits the activity of PRC2.
Synonyms: hPHF1; PCL1; MTF2L2; TDRD19C
Tractability: Small molecule: a structure with a bound ligand is known. PROTAC: ubiquitination databases record sites on it; its protein half-life has been measured.
Gene: Protein-coding gene on chromosome 6 (33,410,382 to 33,416,453, forward strand). Ensembl gene ENSG00000112511.
Subcellular location: Nucleus; Cytoplasm, cytoskeleton, microtubule organizing center, centrosome
Subcellular location (Human Protein Atlas): Nucleoplasm
Pathways (Reactome):
Gene expression (Transcription): PRC2 methylates histones and DNA
Gene Ontology:
Molecular function: histone H3K36me3 reader activity; histone H3K4me3 reader activity; histone methyltransferase binding; identical protein binding; protein binding; transcription corepressor binding; chromatin binding
Biological process: DNA repair-dependent chromatin remodeling; heterochromatin formation; negative regulation of gene expression, epigenetic; negative regulation of transcription by RNA polymerase II
Cellular component: centrosome; ESC/E(Z) complex; nucleoplasm; nucleus; site of double-strand break
Genetic constraint (gnomAD): Loss-of-function variants: 16 observed, 71.9 expected, observed/expected ratio (o/e) 0.22, 90% interval 0.15 to 0.34. The upper end of that interval is the gene's LOEUF score, 0.34, which puts it in group 1 of 6, group 1 being the genes least tolerant of losing a copy. Missense variants: 515 observed, 759.31 expected, observed/expected ratio (o/e) 0.68, 90% interval 0.63 to 0.73. Synonymous variants: 274 observed, 288.54 expected, observed/expected ratio (o/e) 0.95, 90% interval 0.86 to 1.05.
Homologues: Orthologues: chimpanzee PHF1 (99% identical), macaque PHF1 (99% identical), rabbit PHF1 (98% identical), dog PHF1 (97% identical), pig PHF1 (95% identical), guinea pig PHF1 (94% identical), rat Phf1 (93% identical), mouse Phf1 (92% identical), tropical clawed frog phf1 (57% identical), zebrafish phf1 (36% identical), Drosophila melanogaster Pcl (27% identical). Paralogues in human: MTF2 (40% identical), PHF19 (37% identical).
Diseases named in the same sentence as PHF1 in open-access papers:
PHF1 is named in the same sentence as 56 diseases in open-access papers, as found by Europe PMC text mining. Sharing a sentence is not in itself a finding about the gene and the disease. The quoted sentences say what the papers report.
tauopathy (27 papers, 2012 to 2025). Neurodegenerative disorders involving deposition of abnormal tau protein isoforms (tau proteins) in neurons and glial cells in the brain. "Both mAbs detected pathological tau lesions in all of the tauopathy brain sections to a similar extent as the diagnostic standard PHF1 antibody, which binds tau phosphorylated at Ser396 and Ser404." (PMID 33148293, 2020). "PHF1 antibodies recognize both 3R and 4R pathogenic isoforms of tau and were selected because it is widely used for the identification of both astroglial (predominantly 4R) and neuronal (both 3R/4R) tauopathies in CTE." (PMID 38750510, 2024). "In the 4R-Tau specific tauopathies, we observed extensive PHF1 positive staining consistent with the presence of astrocytic plaques (CBD), tufted astrocytes (PSP), pre-tangles, and dystrophic neurites in the basal ganglia." (PMID 31796108, 2019). "Antibody MHT2 was further used to stain human cases of tauopathy, with PHF1 again used as a positive control for hyperphosphorylated tau pathology." (PMID 30261006, 2018). "Tau hyperphosphorylation at PHF1 epitope, largely mediated by GSK3β, affects microtubule dynamics and NFT accumulation, which is considered a hallmark cytopathology in AD and other tauopathies." (PMID 29982852, 2018). "Both CP13 and PHF1 detected striking amounts of tauopathy in the cortex and hippocampus of late stage rTg4510 mice on either background and tau pathology was found in both the cell body and the neuropil." (PMID 24428919, 2014). "Immunohistochemical (IHC) staining with CP13 and PHF1 antibodies was used to compare tauopathy in rTg4510B6 and rTg4510 mice." (PMID 24428919, 2014). "Additional characterization of the Qβ-AT8 and Qβ-PHF1 vaccines in other animal models of AD and tauopathy may be necessary to better understand the clinical translatability and clinical utility of these vaccines." (PMID 38946961, 2024). "Similarly, PHF1 antibody also showed a similar outcome with PS/E2h mice showing higher tauopathy in the contralateral hippocampus (p < 0.01) and only a trend in ipsilateral hippocampus (p = 0.077) relative to PS/E4h mice." (PMID 35440098, 2022). "It is unclear whether or not the hyperphosphorylation is a cause or result of disease, however, the immunostaining of postmortem brains with anti-phospho-tau antibodies such as AT8, AT180, and PHF1 is usually used as a definitive diagnosis of AD and tauopathy." (PMID 29467609, 2018). "The central purpose of this investigation was to determine if either the AT8 or PHF1 phospho-tau epitopes, when displayed on Qβ VLPs, would be efficacious in generating targeted antibody responses, reducing tau pathology, and rescuing cognitive deficits in the rTg4510 model of tauopathy." (PMID 38946961, 2024). "To explore the possibility that blast exposure is associated with tauopathy as suggested in a recent study, we processed sections of the frontal and temporal lobes of 5 blast cases with IHC for distinct phosphorylated and conformational tau epitopes using antibodies AT8, CP13, PHF1 and MC1." (PMID 25422066, 2014). "Previous findings have suggested similarities between mitotic Tau phosphorylation and hyperphosphorylation observed in tauopathies, particularly at sites such as AT8, PHF1, S214, and S422." (PMID 41148853, 2025). "Nevertheless, and most importantly for our study, the bTVBT2 inside the AD retinal microglia was positive for both PHF-1 and AT8, two well-known markers for tauopathy in the brain." (PMID 38167557, 2024). "Next, we used immunoblotting to evaluate brain levels of tauopathy by assessing tau phosphorylation markers (RZ3, CP13 and PHF1) and total tau (DA9) in the hippocampus." (PMID 38750510, 2024).
tauopathy (continued). "Similarly, the pT181 tau epitope becomes pathologically modified earlier in the disease than both the AT8 and PHF1 sites which could explain why our previous Qβ-pT181 vaccine demonstrated the highest efficacy in the same animal model of tauopathy using the same vaccine dosing schedule." (PMID 38946961, 2024). "Interestingly, a significant increase in the detection of PHF1 tau was observed at both 5- and 8-months timepoints, suggesting increased phosphorylation at S396/404 may be an earlier event in the progression of AD and related tauopathies." (PMID 35359570, 2022). "To detect tau phosphorylated at S202 and S396/404–sites that are hyper-phosphorylated in human tauopathies–we used the phospho-tau antibodies CP13 and PHF1, respectively." (PMID 24428919, 2014). "Cases from the various tauopathies did not display any significant difference in PHF1 immunoreactivity." (PMID 35246269, 2022). "Following the treatments, the effectiveness of different kinase inhibitors was assessed using the tauopathy-relevant tau antibodies through tau-immunoblotting, including the sites: pSer202/pThr205 (AT8), pThr181 (AT270), pSer202 (CP13), pSer396/pSer404 (PHF-1), and pThr231 (RZ3)." (PMID 32692785, 2020). "In fact, postmortem diagnosis of tauopathies, including AD, is done by immunohistochemical staining of patients' brains with anti-tau phospho-specific antibodies such as AT8 (Ser202 and Thr205), AT180 (Thr231 and Ser235) and PHF1 (Ser396 and Ser404)." (PMID 29467609, 2018). "MHT2 again appears to recognize late stage tauopathy in the form of somatic NFTs, and does not show an affinity for tau containing plaques, neurites, or astrocytic tufts that PHF1 recognizes." (PMID 30261006, 2018). "The PHF-1 (phospho-Ser396/Ser404) is a later-stage tauopathy marker, and a 24-hour LPS treatment may not strongly induce phosphorylation at these sites." (PMID 41353558, 2025). "Overall, the Qβ-PHF1 vaccinated rTg4510 group exhibited some rescue of hippocampal-dependent memory deficits observed in the Qβ Control vaccinated rTg4510 group while the Qβ-AT8 vaccine offered no protection against tauopathy-induced memory deficits." (PMID 38946961, 2024). "Although the exact mechanism of tauopathy-induced disorders is not yet elucidated, the immunostaining of autopsy brains with anti-p-tau antibodies, including AT8 (pSer202/pThr205), and PHF-1 (pSer396/pSer404) are utilized as a diagnostic method of AD and tauopathy-related diseases." (PMID 32692785, 2020). "Next, we examined the trypsin-resistant tau bands from various tauopathy brains, including AD, PiD, CBD, PSP, a combination case of CBD and PSP (CBD + PSP), and MAPT, by means of 1.0 mg/mL trypsin treatment followed by immunoblotting with TauC4, AT180, 12E8, PHF1, pS409 and AP422." (PMID 26538150, 2016).
endometrial stromal sarcomas (12 papers, 2015 to 2025). "In summary, most studies on the role of PCL proteins in cancer refer to the oncogenic role of PHF19 in a variety of cancers and PHF1 gene translocations in endometrial stromal sarcoma and ossifying fibromyxoid tumors." (PMID 37107696, 2023). "The PHD finger protein-1 (PHF1) gene, mapping on chromosome band 6p21, was first identified as being rearranged in low-grade endometrial stromal sarcoma (LG-ESS)." (PMID 29721194, 2018). "In addition, most low-grade endometrial stromal sarcomas have a JAZF1-SUZ12 gene fusion or PHF1 gene rearrangement." (PMID 40417005, 2025). "Furthermore, PHF1 is recurrently translocated in two rare cancer types: ossifying fibromyxoid tumors and endometrial stromal sarcoma." (PMID 37107696, 2023). "However, the MEAF6-SEPSEC rearrangement detected in one patient, GIST_150, is noteworthy since MEAF6 has recently been reported as translocated with PHF1 in endometrial stromal sarcomas and in ossifying fibromyxoid tumors." (PMID 26544626, 2015). "The fusions reported in endometrial stromal sarcomas (ESS) include JAZF1-SUZ12, YWHAE-FAM22, ZC3H7-BCOR, MBTD1-CXorf67, and fusions of PHF1 with JAZF1, EPC1, and MEAF6." (PMID 35627126, 2022). "The majority of low-grade endometrial stromal sarcomas (LG-ESSs) harbor a fusion gene, most commonly involving JAZF1, SUZ12, and/or PHF1 genes, i.e., JAZF1-SUZ12 fusion (80%), JAZF1-PHF1 fusion (6%), or EPC1-PHF1 fusion (4%)." (PMID 32921307, 2020). "EPC1 is found fused to PHF1 in endometrial stromal sarcomas and ossifying fibromyxoid tumors, and the present study also identified the EPC1-PHF1 fusion in the round cell sarcoma case #28." (PMID 32825119, 2020). "No PHF1 and JAZF1 break-apart signals did not support the diagnosis of low grade endometrioid stromal sarcoma, in which, more than 50% cases harbor gene fusions." (PMID 32290854, 2020).
Cognitive impairment (8 papers, 2016 to 2024). Abnormal cognition is characterized by deficits in thinking, reasoning, or remembering. "The Qβ-PHF1 vaccine exhibited some protection against cognitive deficits, reductions in tau pathology with a preferential reduction of insoluble tau aggregates, and blunted microgliosis." (PMID 38946961, 2024). "While both vaccines were highly immunogenic, eliciting high-titer antibody responses against their respective target in the vaccinated animals, only the Qβ-PHF1 vaccine was able to reduce tau pathology and rescue cognitive deficits." (PMID 38946961, 2024). "However, only Qβ-PHF1 rescued cognitive deficits, reduced soluble and insoluble pathological tau, and reactive microgliosis in a 4-month rTg4510 model of FTD." (PMID 38946961, 2024). "PHF1, which labels phosphorylation at epitopes Ser396 and Ser404, is thought to be a marker of presence of neurofibrillary tangles, and neurofibrillary tangles have been found to be correlated with the degree of cognitive deficits in several studies assessing humans." (PMID 34769068, 2021). "Also, these results strongly suggested that age-related mitochondrial impairment in the synapses could be due, almost in part, to the accumulation of phosphorylated tau PHF-1 in the synaptic mitochondria, possibly inducing age-related synaptic and cognitive impairment." (PMID 33627790, 2021). "In the current study, we discovered that repeated sevoflurane anesthesia increased hippocampal levels of total ApoE, full‐length ApoE, ApoE fragments, Tau phosphorylation (AT8 and PHF1), as well as cognitive impairment in young mice, but not in adult animals." (PMID 35810473, 2022). "Sevoflurane anesthesia enhanced ApoE mRNA, total ApoE, full‐length ApoE, ApoE fragments, Tau phosphorylation (AT8 and PHF1), and cognitive impairment in young mice, but not in adult mice." (PMID 35810473, 2022). "We examined the immunoreactivity of GT-38 and PHF1 to pathological tau aggregates in CA1 of the hippocampus from a cohort of patients with AD and no cognitive impairment to assess the concordance of these antibodies in a range of varying Braak stages." (PMID 30832741, 2019).
Alzheimer disease (5 papers, 2015 to 2022). A progressive, neurodegenerative disease characterized by loss of function and death of nerve cells in several areas of the brain leading to loss of cognitive function such as memory and language. "To assess tau pathology in the brains of P301S+/− and P301S+/−,KIF5B+/− mice, we used AT8, AT100, AT180, and PHF1 monoclonal antibodies, which are commonly used as diagnostic markers of Alzheimer’s disease." (PMID 36387285, 2022).
dementia (5 papers, 2016 to 2021). Loss of intellectual abilities interfering with an individual's social and occupational functions. "Furthermore, E2-treatment also reduced BCCAO induction of dementia-related proteins expression such as p-tau (PHF1), total ubiquitin, and Aβ1-42, when examined at 6 m after BCCAO." (PMID 28205591, 2017). "P-Tau Ser396/Ser404 (PHF-1) has been previously shown to localise in the nucleus but not nucleolus, of a patient with presenile dementia with motor neuron disease." (PMID 30064522, 2018).
endometrial stromal tumor (5 papers, 2013 to 2025). Neoplasms of the endometrial stroma that sometimes involve the myometrium. "Recurring chromosomal aberrations involving PHF1 may be a cause of endometrial stromal tumors." (PMID 28415633, 2017). "OFMT is the second neoplasm to be identified, in addition to endometrial stromal tumor, in which PHF1 is involved in fusions with ectopic sequences." (PMID 23599783, 2013). "Additionally, several studies have confirmed that UTROSCT lacks the characteristic JAZF-1-SUZ12 gene fusion or PHF1 gene rearrangement of endometrial stromal tumors and does not have the FOXL2 and DICER1 gene mutations unique to ovarian sex cord stromal tumors." (PMID 40417005, 2025). "For example, UTROSCT differs from endometrial stromal neoplasms (including those with sex cord stromal differentiation) in that it typically does not exhibit the JAZF1-SUZ12 fusion or PHF1 rearrangements." (PMID 38276058, 2024).
ossifying fibromyxoid tumor (5 papers, 2020 to 2024). A rare soft tissue tumor of uncertain lineage characterized by the presence of neoplastic spindle to round cells forming cords in a fibromyxoid stroma. "In the development of ossifying fibromyxoid tumor (OFMT), PHF1 modulates transcriptional repression by integrating with the Polycomb Repressive Complex 2 (PRC2), which is responsible for the histone mark lysine 27 on histone H3 (H3K27me3)." (PMID 38813086, 2024). "Additionally, PHF1 gene rearrangements and EP400-PHF1, EPC1-PHF1, and MEAF6-PHF1 fusion genes have been shown in ossifying fibromyxoid tumors." (PMID 35225876, 2022).
breast carcinoma (3 papers, 2018 to 2023). "Although PHF1 appears to function mostly as a tumor suppressor, in the context of breast cancer cells, PHF1 has also been described as promoting cellular proliferation." (PMID 37107696, 2023). "Promising proteomic markers of breast cancer (SPG7, ADRB1, SMCO4, PHF1, and PSMG1) from NPCs identified in this study should be further verified in larger patient groups." (PMID 38138918, 2023). "The PHF1 protein was shown to be overexpressed, while the SMCO4 and PSMG1 proteins had medium expression levels in breast carcinoma cells, all with low tissue specificity." (PMID 38138918, 2023). "Of the transcriptional regulators, GATA2, PHF1 and SIN3A were previously reported to be involved in breast cancer." (PMID 30375428, 2018).
epilepsy (3 papers, 2021 to 2025). A brain disorder characterized by episodes of abnormally increased neuronal discharge resulting in transient episodes of sensory or motor neurological dysfunction, or psychic dysfunction. "Proteins altered in epilepsy were significantly enriched in proteins that interact with PHF1-immunoreactive pTau (55/125 pTau interacting proteins; p = 1.06 × 10–15) in advanced AD." (PMID 38289539, 2024). "In epilepsy lesions, we noted layer I labeling often in perilesional regions with PHF1, CP13, and AT8 and a relative lack of labeling with AT180 and AT100, the later including phosphorylation sites at Ser 214, which therefore differs from late developmental patterns." (PMID 40299318, 2025). "We confirmed common AD tau phosphorylation sites across epilepsy pathologies, with more consistent labeling with AT8 and CP13 compared to PHF1, AT100, and AT180, the later epitopes showing more variability; for example, PHF1 and AT180 were relatively low in SWS and cavernoma." (PMID 40299318, 2025).
neuroblastoma (3 papers, 2012 to 2025). Neuroblastoma (NB) is the most common solid, extracranial childhood tumor. "Thus, we next determined the effect of DMSO on tau phosphorylation at the AT8, AT180 and PHF-1 phosphoepitopes using SH-SY5Y human neuroblastoma cells stably transfected to express human tau with 3 microtubule binding domains (htau SH-SY5Y cells)." (PMID 22768202, 2012). "In D. melanogaster models of autophagy, particularly those expressing the 2N4R-Tau, and in neuroblastoma cells, the downstream effects of the insulin receptor signaling cascade lead to tau hyperphosphorylation at AT8 and PHF1 (PHD finger protein 1) residues." (PMID 38028759, 2023).